MET (MET proto-oncogene, receptor tyrosine kinase)
Diseases named in the same sentence as MET in open-access papers (continued):
Sharing a sentence is not in itself a finding about the gene and the disease.
ovarian carcinoma (continued). "Once again, these results data indicate that HGF/MET overexpression has a significant role in promoting cell migration and matrix degradation and therefore ovarian cancer progression." (PMID 23320251, 2012). "HGF/MET pathway plays a major role in ovarian cancer onset and progression including invasiveness and metastasis." (PMID 23320251, 2012). "MET was expressed in normal ovarian epithelium as well as in benign tumors and it was overexpressed in a subset (30–40%) of epithelial ovarian cancer." (PMID 23320251, 2012). "The overexpression of MET protein in ovarian carcinoma showed a substantial variation between tumors versus normal ovary." (PMID 23320251, 2012). "Only the results in the coming years will tell on the efficacy of MET inhibitors in solid tumors, namely, ovarian cancer." (PMID 23320251, 2012). "In this paper, we will discuss the HGF/MET pathway in ovarian cancer, its clinical significance, and its potential use as a target therapy in the future." (PMID 23320251, 2012). "Several studies confirmed the important role of HGF/MET signaling in the transformation of surface ovarian epithelial cells and in the growth and dissemination of ovarian cancer." (PMID 21962244, 2011). "Blocking the MET signaling by the MET inhibitors, PF-2341066, or by specific MET RNAi had antiproliferative effects and reduced tumor metastasis in ovarian cancer cells, possibly by suppressing MET-dependent PI3-K/AKT and RAF/MAPK signaling pathways." (PMID 21962244, 2011). "The MET receptor tyrosine kinase and its ligand (hepatocyte growth factor, HGF) are highly expressed in ovarian cancers, and MET inactivation by small molecular inhibitor and siRNA reduced tumor burden and metastasis in nude mice with ovarian cancer." (PMID 21962244, 2011). "Recently, Sawada and colleagues have analyzed c-MET role in ovarian cancer biology and its possible implication as a therapeutic target; so, it has been established the c-MET over-expression, especially in patients in higher stage disease." (PMID 19949545, 2009). "Moreover, endometriosis cells expressed c-MET at a level similar to ovarian cancer cells, suggesting that endometriosis cells have a similar capacity to migrate and disseminate in the abdominopelvic cavity." (PMID 40076450, 2025). "Our immunohistochemistry analysis showed that the co‐expression of CD24 and MET was associated with poorer patient survival in ovarian cancer than those without." (PMID 38030594, 2024). "Therefore, the HGF/c-MET signal has been used as a therapeutic target in ovarian cancer clinical trials." (PMID 35874635, 2022). "We also discuss that HGF/c-MET-targeted therapy, when combined with chemo drugs, could be an effective strategy for ovarian cancer therapeutics." (PMID 35630066, 2022). "In addition, high levels of HGF are found in malignant ascites of patients with ovarian cancer, which promotes cancer cell migration by activating c-MET." (PMID 35630066, 2022). "We tested whether an increased level of MET expression, resulting in further MET activation, could impair ovarian cancer cell response to PARPi." (PMID 35628590, 2022). "Although few patients with ovarian cancer were included in the phase I clinical trial of a drug targeting HGF/c-MET, the phase II clinical trial of rilotumumab in patients with recurrent epithelial ovarian, fallopian tube, or primary peritoneal carcinoma demonstrated a significant effect." (PMID 35630066, 2022). "Interestingly, in several ovarian cancer cell lines, enhanced sensitivity to carboplatin and paclitaxel with MET inhibition (MK8033) has been correlated with a 47 gene signature." (PMID 33526881, 2021). "miR-199 was reported to have lower expression in ovarian cancer, and this miRNA inhibited the related gene pathway by blocking the activation of the c-MET, HIF1-alpha HIF2-beta, and IKK-beta proteins, and thus might be a therapeutic target." (PMID 34629107, 2021).
ovarian carcinoma (continued). "High MET expression has been linked to shorter OS in ovarian cancer, triple-negative breast cancer (TNBC), and non-small-cell lung cancer patients." (PMID 34069138, 2021). "In addition to HER family members, ovarian cancers also overexpress c-MET receptor, raising a possibility of engaging c-MET/HER dimerization in a sub-group of ovarian cancer." (PMID 31426393, 2019). "In addition, MK8033 has also been identified as a novel drug molecule for targeting MET in ovarian cancer cells." (PMID 31766284, 2019). "c-MET amplification could be used as a prognostic marker in ovarian cancer patients with clear-cell adenocarcinoma." (PMID 29291022, 2017). "In non-adherent ovarian cancer cells, c-MET overexpression caused acquired resistance to cisplatin and paclitaxel through PI3K/AKT and extracellular signal-regulated kinase (ERK) 1/2 signaling." (PMID 29291022, 2017). "We have addressed the effect of HGF, and subsequent inhibition of c-MET, on migration of ovarian cancer cells in both directional (chemotactic) and random migration assays, to more accurately recapitulate the environment and proteins encountered in an in vivo setting." (PMID 26138303, 2015). "Furthermore, high expression of c-MET has been identified in 30–70% of ovarian cancer cases, and correlated with poorer prognosis." (PMID 26138303, 2015). "Furthermore, a luciferase reporter assay confirmed that c-MET is a target of MACC1 in ovarian cancer cells." (PMID 25009663, 2014). "In conclusion, the current study reported that MACC1 downregulation may effectively suppress the malignant biological behavior of ovarian cancer and confirmed that c-MET is a target of MACC1." (PMID 25009663, 2014). "The HGF/MET signaling pathway is abnormal in numerous cancers including ovarian cancer." (PMID 23320251, 2012). "The receptor tyrosine kinases (RTKs), including EGFR, ERBB2, PDGFR, VEGFR and MET, are activated in subsets of ovarian cancer, suggesting that these kinases might represent novel therapeutic targets." (PMID 21962244, 2011). "However, there were only seven ovarian cancer patients out of 635 with amplified MET expression." (PMID 31766284, 2019). "Interestingly, only one other study to our knowledge, has determined the relative expression of all four HER family members and c-MET in tissue arrays from 202 tumours from ovarian cancer patients (172 FIGO stages I-IV and 30 stages unknown)." (PMID 29731973, 2018). "Finally, a luciferase reporter assay and western blot analysis were used to confirm whether MACC1 functions as a metastatic promoter in ovarian cancer by targeting c-MET." (PMID 25009663, 2014). "HGF, c-MET and PTTG1 are potential therapeutic targets for inhibiting the abdomen–pelvic/peritoneal spread of endometriosis and ovarian cancer." (PMID 40076450, 2025). "The observed cell migration was blocked by c-MET inhibition, suggesting that HGF/c-MET signaling mediates cell migration in endometriosis and ovarian cancer." (PMID 40076450, 2025). "However, adding HGF, which induces MET phosphorylation, overcame the inhibition of an ovarian cancer cell invasion caused by α5β1 blocking antibodies or siRNA, indicating that integrins act upstream of MET in an HGF-independent manner, playing a crucial role in MET activation." (PMID 39769452, 2024). "In our miRNA transcriptome and putative target genes analyses, miR‐181a was downregulated in CD24‐high ovarian cancer cells compared to CD24‐low and predicted to bind to CD24 and MET 3'UTRs." (PMID 38030594, 2024). "The c-MET inhibitor crizotinib demonstrated synergy with PARP inhibition in preclinical breast, lung and ovarian cancer models." (PMID 37430137, 2023). "In the preclinical model of ovarian cancer, YYB-101 blocked HGF, leading to the inhibition of the progression of ovarian cancer cells through downstream signaling of the c-MET axis." (PMID 35630066, 2022).
ovarian carcinoma (continued). "Many studies have been conducted to treat ovarian cancer using small molecules and antibody drugs, which are new candidates targeting HGF/c-MET." (PMID 35630066, 2022). "Hepatocyte growth factor receptor (HGFR), also known as c-mesenchymal–epithelial transition factor (c-MET), plays a crucial role in the carcinogenesis of epithelial ovarian cancer (EOC)." (PMID 36359213, 2022). "A study on the efficacy and mechanism of action of foretinib, an orally available multi-kinase inhibitor of c-MET under development by GlaxoSmithKline (GSK), was conducted in a preclinical model of ovarian cancer." (PMID 35630066, 2022). "As a result, multiple studies have verified the synergistic reduction of tumor development in ovarian cancer cells in vitro and in vivo when chemo drugs are combined with HGF or c-MET targeting." (PMID 35630066, 2022). "MET overexpression was shown to trigger an increase of BRCP/ABCG2 and ABCB1/MDR1 expression in doxorubicin-resistant (DR) ovarian carcinoma cells and in cisplatin-resistant NSCLC cell lines respectively." (PMID 33526881, 2021). "Two patients’ biopsies (patient 28 with ovarian carcinoma and patient 30 with esophageal carcinoma) had signal above the LLQ for c-MET phosphorylated at either Y1234/1235 or pY1356 in both biopsies." (PMID 34180036, 2021). "It was reported that FER regulated GAB1 and MET phosphorylation and activated SHP2-ERK signaling in ovarian cancer." (PMID 34295819, 2021). "The combination of a MET inhibitor (METi) and a PARPi has been shown to synergistically inhibit growth in TNBC cell lines as well as in ovarian cancer cell lines." (PMID 34069138, 2021). "In PDX isolates of ovarian cancer cells, however, the expression and phosphorylation of ERBB1, ERBB2, c-MET, c-KIT, and c-SRC was reduced by drug combination exposure." (PMID 31380285, 2019). "Other CARs mentioned in this review that use the CD28ζ costimulatory domain include L1CAM CARs for ovarian cancer in mice, MET CARs for MPM, MUC16 CARs in mouse models of ovarian cancer and peritoneal carcinomatosis, and NKG2D CARs in Ewing's sarcoma models." (PMID 30804938, 2019). "YYB-101 suppressed the phosphorylation of the HGF receptor c-MET and inhibited the migration and invasion of SKOV3 and A2780 ovarian cancer cells." (PMID 31355133, 2019). "Next, we examined the expression pattern of other growth factor receptors (c-MET and IGF-1R) and one of the putative ovarian cancer stem cell markers, CD44, in tumour specimens from these patients." (PMID 29731973, 2018). "In our previous report, c-MET expression was enhanced in the doxorubicin-resistant ovarian cancer cells, which affected BCRP levels via PI3K/AKT activation, suggesting a novel link between c-MET and BCRP-mediated resistance." (PMID 29291022, 2017). "Interfering RNA-induced stable inhibition of NRF2 in ovarian carcinoma SKOV3 and renal carcinoma A498 reduced the levels of c-MET and EGFR." (PMID 29291022, 2017). "A number of c-MET inhibitors and HGF antagonists are currently under investigation, in both pre-clinical models of ovarian cancer, and clinical trials for multiple cancer types (reviewed in6 and19)." (PMID 26138303, 2015). "The objective of this study was to determine the efficacy of a novel, highly potent, orally-bioavailable c-MET inhibitor, INC280, in blocking cell phenotypes important in ovarian cancer metastasis." (PMID 26138303, 2015). "miR-31 directly targets the 3′-UTR of MET and increases the PTX sensitivity of ovarian cancer cells in an animal model." (PMID 25295252, 2014).
ovarian carcinoma (continued). "Lower expression of miR-31 and higher expression of MET (also known as c-Met or hepatocyte growth factor receptor) were significantly correlated with PTX resistance and poor prognosis in ovarian cancer patients." (PMID 25295252, 2014). "Next, we will discuss the HGF/MET axis alterations in ovarian cancer and its clinical implication, as well as the potential therapeutic use of HGF/MET inhibitors in ovarian cancer." (PMID 23320251, 2012). "Inhibition of total EGFR, ERBB2, MET and AXL expression was seen in all ovarian cancer cell lines after treatment with 17-AAG in serum-containing medium for 48 hours." (PMID 21962244, 2011). "EGFR, MET, and AXL activation in the ovarian cancer lines was comparable to that in MESO924 cells, which are known to feature strong activation of these RTK." (PMID 21962244, 2011). "Our studies demonstrated that simultaneous activation of multi-RTKs including EGFR, ERBB2, MET, and AXL contributes to ovarian cancer cell proliferation and survival." (PMID 21962244, 2011). "Our results suggested that the simultaneous activation of multi-RTK (EGFR, ERBB2, ERBB4, MET and/or AXL) in individual ovarian cancer contribute to the drug resistance to individual RTK inhibitors in ovarian cancer." (PMID 21962244, 2011). "The HSP90 inhibition led to the dephosphorylation and degradation of EGFR, ERBB2, ERBB4, MET and AXL in various ovarian cancer cells." (PMID 21962244, 2011). "Herein, we demonstrate co-activation of multiple RTKs (EGFR, ERBB2, ERBB4, MET and/or AXL) in individual ovarian cancer cell lines and primary tumors." (PMID 21962244, 2011). "Immunoblotting evaluations of ovarian cancer total cell lysates also demonstrated inactivation of EGFR, ERBB2, and MET after 17-AAG treatment." (PMID 21962244, 2011). "In the current studies we demonstrate the simultaneous activation of multiple RTKs - including EGFR, ERBB2, MET, and/or AXL - in individual ovarian cancer cell lines and primary tumors." (PMID 21962244, 2011). "To determine if HGF/c-MET signaling mediated cell migration in endometriosis and non-HGSC ovarian cancer, we first assessed c-MET expression level using qRT-PCR." (PMID 40076450, 2025). "When HGF/c-MET-targeted molecules were applied to ovarian cancer in various clinical trials, no specific therapeutic efficacy was observed." (PMID 35630066, 2022). "In this review, we explain the properties of the hepatocyte growth factor (HGF)/mesenchymal-epithelial transition factor (c-MET) and how the signaling pathway of HGF/c-MET is activated in different cancers and involved in tumorigenesis and metastasis of ovarian cancer." (PMID 35630066, 2022). "In addition, c-MET inhibitors such as PF-2341066, foretinib and DCC-2701 have shown effective antitumor activities in ovarian cancer xenograft models." (PMID 31355133, 2019). "The aim of the present study was to determine the relative expression, cellular location, and prognostic significance of HER-family members, the EGFR mutant (EGFRvIII) c-MET, IGF-1R and the cancer stem cell biomarker CD44 in 60 patients with FIGO stage III and IV ovarian cancer." (PMID 29731973, 2018). "Studies showed that NK4 could inhibit ovarian cancer cell migration, tumor growth, and peritoneal dissemination in vivo, indicating that NK4 could be an attractive target for therapy in inhibiting HGF/MET pathway." (PMID 23320251, 2012). "The findings reported here are important also when approaching tumour therapy from the perspective of inhibiting HGF and MET, HGF is a Janus-faced molecule, which sensitizes ovarian cancer cells to chemotherapeutics, but is alone able to trigger cancer cell growth and invasiveness." (PMID 22999213, 2012). "In our present study, PHA-665752, a MET inhibitor, had mild effect in OVCA429 cell viability, and PHA-665752 inhibition of viability did not correlate with baseline MET tyrosine phosphorylation in ovarian cancer." (PMID 21962244, 2011).
ovarian carcinoma (continued). "Several therapeutics, including small molecules and antibodies, such as foretinib, cabozantinib and YYB-101, have been developed that target the HGF/c-MET pathway and have been tested in clinical trials in ovarian cancer patients, yet none has shown significant efficacy." (PMID 40076450, 2025). "However, to our knowledge, there is currently no comprehensive study on the relative expression, cellular location and prognostic significance of all members of the HER family, c-MET, IGF-1R, and the putative ovarian cancer stem cell biomarker in patients with ovarian cancer." (PMID 29731973, 2018). "In doxorubicin-resistant ovarian carcinoma cells, BCRP overexpression was mediated by the c-MET elevation and resultant PI3K/AKT activation, and thus, the inhibition of c-MET could repress the plasma membrane BCRP level and enhanced doxorubicin-induced cell death." (PMID 29291022, 2017). "However, despite these limitations, to our knowledge this is one of the first studies to substantially compare the demographic and clinical characteristics of ovarian cancer patients with MET altered patients and their response to treatment with c-Met inhibitors." (PMID 25593979, 2014). "Thus, indicating that while the paracrine interaction of HGF/MET is important in normal ovarian physiology, the autocrine HGF/MET loop seems to be important in ovarian cancer onset and maybe progression." (PMID 23320251, 2012). "However, none have reached to Phase III clinical trials regarding ovarian cancer, suggesting that the mere inhibition of MET might not be sufficient to overcome this miserable disease." (PMID 25839163, 2015). "However, in ovarian cancer, it seemed that HGF/MET did not regulate angiogenesis." (PMID 23320251, 2012).